ADGRE1 (adhesion G protein-coupled receptor E1)
Description:
Orphan receptor involved in cell adhesion and probably in cell-cell interactions specifically involving cells of the immune system. May play a role in regulatory T-cells (Treg) development.
Synonyms: EMR1; TM7LN3
Tractability: Antibody: UniProt places it where antibodies can reach, with high confidence; its Gene Ontology location is reachable by antibodies, with high confidence; UniProt predicts a signal peptide or a membrane-spanning region.
Gene: Protein-coding gene on chromosome 19 (6,887,566 to 6,940,459, forward strand). Ensembl gene ENSG00000174837.
Subcellular location: Cell membrane
Pathways (Reactome):
Signal Transduction: Class B/2 (Secretin family receptors)
Gene Ontology:
Molecular function: G protein-coupled receptor activity; calcium ion binding; transmembrane signaling receptor activity
Biological process: cell adhesion; G protein-coupled receptor signaling pathway; cell surface receptor signaling pathway
Cellular component: plasma membrane; cell periphery; external side of plasma membrane; membrane
Genetic constraint (gnomAD): Loss-of-function variants: 82 observed, 103.57 expected, observed/expected ratio (o/e) 0.79, 90% interval 0.66 to 0.95. The upper end of that interval is the gene's LOEUF score, 0.95, which puts it in group 4 of 6, group 1 being the genes least tolerant of losing a copy. Missense variants: 1,030 observed, 1,112 expected, observed/expected ratio (o/e) 0.93, 90% interval 0.88 to 0.98. Synonymous variants: 398 observed, 415.09 expected, observed/expected ratio (o/e) 0.96, 90% interval 0.88 to 1.04.
Homologues: Orthologues: chimpanzee ADGRE1 (97% identical), macaque ADGRE1 (79% identical), dog ADGRE1 (71% identical), mouse Adgre1 (68% identical), rat Adgre1 (66% identical). Paralogues in human: ADGRE2 (30% identical), ADGRE3 (27% identical), ADGRE5 (27% identical), ADGRL3 (24% identical), ADGRL1 (23% identical), ADGRL2 (22% identical), ADGRL4 (20% identical), ADGRD1 (19% identical), ADGRB2 (18% identical), ADGRB1 (18% identical), ADGRF5 (17% identical), ADGRB3 (16% identical), and 30 more.
Diseases named in the same sentence as ADGRE1 in open-access papers:
ADGRE1 is named in the same sentence as 73 diseases in open-access papers, as found by Europe PMC text mining. Sharing a sentence is not in itself a finding about the gene and the disease. The quoted sentences say what the papers report.
Obesity (15 papers, 2010 to 2024). Accumulation of substantial excess body fat. "Still, obesity led in liver to a significant increase of macrophage marker Adgre1 expression." (PMID 34608215, 2021).
breast cancer (3 papers, 2021 to 2024). A primary or metastatic malignant neoplasm involving the breast. "We found that inhibition of mononuclear phagocytes altered the expression of F4/80 (Adgre1) in mammary tissue and reversed the inhibitory effect of voluntary wheel running on mammary tumor growth." (PMID 33552733, 2021). "However, clodronate also inhibited mammary tumor signal in sedentary mice, in conjunction with an expected decrease in gene and protein expression of the myeloid antigen, F4/80 (Adgre1), in mammary tissue." (PMID 33552733, 2021).
colitis (3 papers, 2018 to 2022). Inflammation of the colon. "We observed that 5% DSS feeding to wild-type (WT) mice resulted in a significant increase in the expression of MPR8 and F4/80 (also known as Adgre1), markers commonly used to detect myeloid cells, indicating that myeloid cell infiltration is increased in DSS-induced colitis." (PMID 29967068, 2018).
colon cancer (3 papers, 2020 to 2024). "Lymphocyte antigen 6 complex locus G6D (LY6G), protein tyrosine phosphatase receptor type C (CD45), and adhesion G protein-coupled receptor E1 (F4/80) are used as inflammatory infiltration marker for colon cancer progression and metastasis marker." (PMID 32131398, 2020).
fatty liver disease (3 papers, 2017 to 2024). A reversible condition wherein large vacuoles of triglyceride fat accumulate in liver cells via the process of steatosis. "Reduce the expression of macrophage marker adhesion G protein-coupled receptor E1 (ADGRE1) and M1 macrophage marker integrin α x (ITGAX), alleviate the inflammatory reaction and improve the liver steatosis." (PMID 37361209, 2023). "Third, as inflammation is a critical factor in the progression of fatty liver disease from simple steatosis to NASH, we also analyzed two inflammatory marker genes - adhesion G protein-coupled receptor E1 (Adgre1, also named Emr1 or F4/80) and chemokine (C-C motif) ligand 2 (Ccl2, also named MCP-1)." (PMID 28300161, 2017).
nephritis (3 papers, 2017 to 2024). Inflammation of renal tissue. "Expression of Fn1, Acta2, Tgfb1, Adgre1 or Ccl2 was tended to be reduced in Rosa-CTGF cKO mice with nephritis, but not significant." (PMID 28191821, 2017). "In addition to the increases in the expression levels of fibrotic makers such as Tgfβ1, Acta2, and Fn1, the glomerular mRNA expression of MCP-1 (Ccl2) and F4/80 (Adgre1) is increased in the control mice with anti-GBM nephritis, and this increase is reduced in the Rosa-CTGF cKO mice with nephritis." (PMID 30123390, 2018). "The glomerular Ccl2 and Adgre1 expression and the M1/M2 macrophage marker ratio were decreased in Rosa-CTGF cKO and Pdgfra-CTGF cKO mice, indicating that CTGF expression particularly in mesangial cells is critical to induction of inflammation in anti-GBM nephritis." (PMID 28191821, 2017).
Sepsis (3 papers, 2020 to 2025). Sepsis is defined as life-threatening organ dysfunction caused by a dysregulated host response to infection. "In addition, IL-1R2 expression is minimal in cluster 9, which co-expressed Adgre1, Clec4f and Tim4 and identified as resident macrophages, namely Kupffer cells in the liver, and this expression did not increase in response to sepsis." (PMID 41293423, 2025).
atherosclerosis (2 papers, 2020). A disease characterized by the build-up of fatty material and calcium deposition in the arterial wall resulting in partial or complete occlusion of the arterial lumen. "Atherosclerosis-associated monocytes/macrophages showed high expressions of Adgre1, Cd14, Fcgr1, and Csf1r and a low expression of Ly6c2." (PMID 33013913, 2020).
diabetes (2 papers, 2022 to 2024). "Expressions of inflammatory cytokines in the glomeruli were assessed and showed that diabetes elevated the expressions of Ccl2, Tnfa, Il1b, Adgre1 (F4/80), and Itgam (CD11b) in both PPKM2Tg and WT mice, but they were attenuated in diabetic PPKM2Tg mice." (PMID 35133981, 2022). "Conversely in subjects with low-apoB, LDL/ATP-induced WAT IL-1β-secretion was associated in the direction of lower diabetes risk, associating positively with IS and negatively with WAT expression of ADGRE1 and MCP1." (PMID 39511203, 2024).
inflammatory bowel disease (2 papers, 2018 to 2022). A spectrum of small and large bowel inflammatory diseases of unknown etiology. "The pattern of regulation of ADGRE1 mRNA, as well as its genomic location, suggests a possible role in genetic susceptibility to inflammatory bowel disease." (PMID 30327653, 2018).
liver fibrosis (2 papers, 2022 to 2024). "However, in renalase knockout mice experiencing liver fibrosis, the expression of the adhesion G protein-coupled receptor E1 (Adgre1), a mature macrophage marker, was significantly higher compared to the controls, indicating, once again, an apparent renalase-macrophage linking." (PMID 36132227, 2022). "The same trend was observed in male Gpr183–/– compared to male WT with significantly lower levels of pro-inflammatory marker Il1β, liver fibrosis markers α-SMA, Col1a1, and Mcp1, and macrophage markers Adgre1 and Cd14." (PMID 39545055, 2024).
melanoma (2 papers, 2023 to 2024). A malignant, usually aggressive tumor composed of atypical, neoplastic melanocytes. "We will also include data, which we obtained when following the expression of Adgre1 after inoculation of cancer cells (melanoma B16-F10) into C57/BL6 mice, which support our idea of similarities between the two models in the present context." (PMID 37459549, 2023).
non-alcoholic steatohepatitis (2 papers, 2021 to 2022). "In a study in the liver, a marker of mature macrophages, Adgre1, was found to be significantly higher in RNLS KO mice during the progression of nonalcoholic steatohepatitis (NASH)." (PMID 34440775, 2021). "Oxidative stress, macrophage infiltration, Adgre1 (a marker of mature macrophages), and TGF-β1 expression are significantly increased in the absence of renalase in non-alcoholic steatohepatitis in vivo." (PMID 35711341, 2022).
pulmonary fibrosis (2 papers, 2015 to 2022). Chronic progressive interstitial lung disorder characterized by the replacement of the lung tissue by connective tissue, leading to progressive dyspnea, respiratory failure, or right heart failure. "Macrophages were omnipresent in lungs of wild type mice subjected to bleomycin-induced pulmonary fibrosis as evident from large amounts of F4/80 (ADGRE1) positive cells." (PMID 26474459, 2015).
bacteremia (1 paper, 2024). "A two-gene signature comprising ADGRE1 and IFI44L demonstrated limited sensitivity for assigning young infants with UTI without bacteremia as having bacterial infection." (PMID 38732074, 2024).
crescentic glomerulonephritis (1 paper, 2022). A histopathologic term for a pattern of diseases characterized by extensive crescent formation in the glomeruli; patients present clinically with rapid deterioration of renal function, and possible progression to end-stage renal failure within weeks or months. "In response to crescentic glomerulonephritis, seven transcriptionally distinct subpopulations of macrophages/monocytes were identified, including two groups of Cd14+ monocytes (Cluster 0, 1) and five clusters of Adgre1+ (F4/80) macrophages (Cluster 3, 4, 7, 8, 9)." (PMID 35484716, 2022).
head and neck cancer (1 paper, 2021). A primary or metastatic malignant neoplasm affecting the head and neck. "By contrast, in the TW2.6 group, Adgre1-positive prototypical macrophages were frequently detected in the tumor margins, a phenomenon reminiscent of ‘immune privileged’ sites detected in clinical head and neck cancer tissues." (PMID 34869001, 2021).
Hypertension (1 paper, 2024). The presence of chronic increased pressure in the systemic arterial system. "To investigate the roles of macrophages in hypertension-induced cardiac dysfunction, we further clustered macrophages, which expressed CD68, Adgre1, Fcgr1 and Csf1r, into 15 small populations." (PMID 38443404, 2024).
IgA nephropathy (1 paper, 2018). "Increased expression levels were found for ADGRL2, ADGRL4, ADGRE1, ADGRE5, ADGRG2, and ADGRG6 in lupus nephritis and diabetic nephropathy, whereby ADGRL2, ADGRL4 and ADGRE5 were also upregulated in IgA nephropathy." (PMID 29468160, 2018). "A role of these genes in vascular and/or inflammation-mediated kidney diseases is further substantiated by the associations with diabetes nephritis (ADGRE1, ADGRE5), lupus nephritis (ADGRE1, ADGRE2, ADGRE5), renal vasculitis (ADGRE2, ADGRE5), IgA nephropathy (ADGRE5) and renal hypertension (ADGRE5)." (PMID 29468160, 2018).
kidney failure (1 paper, 2019). An acute or chronic condition that is characterized by the inability of the kidneys to adequately filter the blood. "To characterise the inflammatory response, we looked at the level of transcripts for the macrophage marker Adgre1 (F4/80) and found this to be significantly less abundant in double KO compared to Pkd1 KO mice at kidney failure." (PMID 31038742, 2019).
pancreatic tumors (1 paper, 2022). "In particular, the addition of ablation to CP4 immunotherapy significantly increased IL-6, Adgre1, Cd64, Ly6a2 and Ly6c2 in the MT4 pancreatic tumors, indicating a population of monocytes and macrophages was particularly enhanced by this combination treatment." (PMID 36451859, 2022).
sarcoidosis (1 paper, 2024). Sarcoidosis is a multisystemic disorder of unknown cause characterized by the formation of immune granulomas in involved organs. "Interestingly, we found a CD68+ F4/80+ (Adgre1) macrophage population in the skin of Tsc2KO sarcoidosis mice that was not present in Tsc2WT mice." (PMID 38353578, 2024).
tumor (33 papers, 2016 to 2025). "The analysis identified the most prominent and significantly altered cell clusters as Tumor-associated macrophages (TAMs) (Clusters 1, 2, and 3), characterized using macrophage markers such as Adgre1 (F4/80), Apoe, Lyz2, Ccr2, and Ccl2." (PMID 41321310, 2025). "In our previous study, the upregulation of epidermal growth factor-like module-containing mucin-like hormone receptor-like 1 (EMR1/ADGRE1) in cancer cells was found to be induced by tumor-associated macrophages (TAMs)." (PMID 38673975, 2024). "In summary, by using a comprehensive bioinformatics analysis, we identified three tumor microenvironment-related genes (ADGRE1, CCL18, and LILRA6) which were closely associated with the prognosis of PCPG." (PMID 33795528, 2021). "Finally, three tumor microenvironment-related genes (ADGRE1, CCL18, and LILRA6) significantly associated with PCPG prognosis were obtained by survival analysis." (PMID 33795528, 2021). "Therefore, we examined the mRNA expression of different specific markers corresponding to cancer-associated fibroblasts (CAF) (Acta2, coding alpha-SMA), endothelial cells (EC) (Pecam1, coding for CD31), and tumor-associated macrophages (TAM) (Adgre1, coding for F4/80)." (PMID 32438553, 2020). "The expression of Adgre1 (F4/80, a macrophage marker) was increased by up to 3-fold in both tumor types, while Gsr, a marker of neutrophils and other granulocytes was not significantly increased in either tumor type." (PMID 36376448, 2023). "In the majority of OC3 tissues, the tumor cells are interdigitated with irregular Adgre1-positive macrophages and are accompanied by high staining backgrounds." (PMID 34869001, 2021). "We also found that mice fed the SDG diet had lower tumor expression of Adgre1, the gene for the macrophage marker F4/80, but F4/80 protein expression was not significantly reduced in the SDG-supplemented mice." (PMID 30367332, 2019). "As elevated expression of CCL2 in tumors is associated with increased tumor growth and poorer overall survival through an increase in macrophage infiltration, the expression of intra-tumoral MCP-1 (Ccl2) and emr1 (Adgre1) was examined." (PMID 27448965, 2016). "For deciphering the precise influence of tumor-associated macrophages (TAM) after X-body treatment, cells with high transcript of CD11b (ITGAM), F4/80 (ADGRE1) and CD115 (Csf1r) were defined as macrophages which accounted for nearly half of the tumor-infiltrating immune cells." (PMID 36451853, 2022). "Therefore, we analyzed the mRNA expression of several immune cell markers (Cd4, Cd8, Klrb1c, CD27, and Adgre1) within the E0771 tumor tissues from WT and Bgn KO mice." (PMID 33966638, 2021). "Given that ‘macrophage’ represents the major (57.2 ± 6.7%) immune cell type residing in the host stroma by CIBERSORTx analysis, immunohistochemistry using an antibody against the panmacrophage marker Adgre1 (F4/80) was performed to visualize the infiltration of macrophages in each tumor section." (PMID 34869001, 2021). "Tumor mRNA levels of Adgre1 were also lower in SDG-supplemented versus control mice (P < 0.05)." (PMID 30367332, 2019). "In contrast, in the tumor AOM/DSS model, less macrophages were found in NoxO1−/−-deficient tumors, as analyzed by conventional immunohistochemistry and a costaining of F4/80 (Adgre1) and the Noxes on mRNA level." (PMID 29867954, 2018). "Probes to detect the following RNAs were used: IL-18, ADGRE1 to visualize macrophages, and mouse mesothelin or human CD19 for tumor antigen detection of PDA7940b tumors or B16-huCD19 tumors, respectively." (PMID 38730243, 2024). "In addition, more ADGRE1 RNA molecules were detected in IMSA101-treated tumors, while RNA-count of the tumor antigens, mouse mesothelin or human CD19, was lower in these cohorts consistent with anti-tumor response." (PMID 38730243, 2024).
tumor (continued). "In our initial analysis, rare non-tumor cells clustered separately from tumor cells, and their identity was further validated by the expression of well-known stromal markers including Vim, Ptprc, Trpm5, Pecam1, Mgp, Cd79a, Itgam, Adgre1, Cd3g, and Marco." (PMID 33821796, 2021). "A linear regression analysis revealed that tumor levels of TNC and CCL2 each correlated with myeloid cell markers, including F4/80 (ADGRE1), CSFR1,and CX3CR1, but not with CCR2, with a higher correlation of TNC than CCL2 at the 3 week time point." (PMID 37176074, 2023).
cancer (10 papers, 2012 to 2024). A tumor composed of atypical neoplastic, often pleomorphic cells that invade other tissues. "In the present study, Mcp-1 mRNA was mainly associated with Adgre1+ macrophages in tumors on both days 5 and 14 after the inoculation of cancer cells." (PMID 34698088, 2021). "EMR1, a member of the adhesion G protein-coupled receptor family (ADGRE1), is a macrophage marker that is abnormally expressed in cancer cells." (PMID 36551877, 2022). "Mcp-1 mRNA-positive cells 14 days after cancer cell inoculation were mainly Adgre1+ macrophages infiltrating around necrotic lesions." (PMID 34698088, 2021). "By ISH, the expression of Adgre1 (F4/80) mRNA (shown as red dots) was detected between cancer cells and some of them were also positive for Mcp-1 mRNA (shown as green dots) (indicated by arrows)." (PMID 31888216, 2019).
infection (9 papers, 2010 to 2025). The state of being infected such as from the introduction of a foreign agent such as serum, vaccine, antigenic substance or organism. "Additionally, Ad-IL8 infection increased the mRNA levels of inflammatory genes such as Adgre1 (the gene encoding F4/80), Tnfa, and Il1b in the livers of HFD-fed mice." (PMID 37895168, 2023). "These two cell types, typically defined by expression of Ly6g (neutrophils) and Adgre1 (F4/80, macrophages), expressed a similar transcriptional program following infection, including S100a8/9, Lcn2, Cxcl1, and Il1b." (PMID 38096412, 2023). "Analyses of the cytokine production (MCP-1 and TNF), macrophage infiltration (estimated by Adgre1 (F4/80) expression), and Nos2 (iNOS) induction in the infected lungs detected a higher expression of Ccl2 (MCP-1), Adgre1, and Nos2 in Trem2−/− mice than in WT mice at day 3 after infection." (PMID 33863908, 2021).
infectious disease (2 papers, 2018 to 2023). A disorder directly resulting from the presence and activity of a microbial, viral, or parasitic agent in humans. "ADGRE1 will provide a useful marker for dissection of infectious disease models in pigs, especially those of the lung where the pig is clearly more human-like." (PMID 30327653, 2018).
ADGRE1 also shares sentences with these, for which no sentence is quoted: Arthritis (3 papers); Hepatic steatosis (2); lymph node metastasis (2); malaria (2); peritonitis (2); steatosis (2); abscesses (1); amyloidosis (1); anaemia (1); bacterial infection (1); cerebral malaria (1); cholestasis (1); Cirrhosis (1); colorectal cancer (1); Coma (1); congenital heart defects (1); diabetic nephropathy (1); Emery-Dreifuss muscular dystrophy (1); endometriosis (1); eosinophilic disorders (1); hepatocellular carcinoma (1); Hyperglycemia (1); Immunodeficiency (1); Infertility (1); Insulin resistance (1); ischemia reperfusion injury (1); ischemic stroke (1); kidney damage (1); kidney diseases (1); Krabbe disease (1).
A further 17 diseases each share a sentence with ADGRE1 in 1 paper.